KRAS (KRas proto-oncogene, GTPase)
Diseases named in the same sentence as KRAS in open-access papers (continued):
Sharing a sentence is not in itself a finding about the gene and the disease.
esophageal adenocarcinoma (10 papers, 2010 to 2025). A malignant tumor with glandular differentiation arising predominantly from Barrett mucosa in the lower third of the esophagus. "The aim of this study was to examine the expression and prognostic impact of human epidermal growth factor receptor 1 (HER1/EGFR) and 3 (HER3), as well as the occurrence of EGFR and KRAS mutations in gastric and esophageal adenocarcinoma." (PMID 26844548, 2016). "In this study we examined the protein expression of EGFR and HER3 as well as the mutational status of EGFR and KRAS in gastric and esophageal adenocarcinoma." (PMID 26844548, 2016). "The aim of this study was to examine the immunohistochemical (IHC) expression of EGFR and HER3, as well as the occurrence of EGFR and KRAS mutations, in gastric and esophageal adenocarcinoma, with particular reference to their relationship with clinicopathological factors, HER2 expression, and OS." (PMID 26844548, 2016). "KRAS amplification is also a potential therapeutic target being explored, and we saw notable enrichment of this alteration in esophageal adenocarcinomas." (PMID 36494601, 2022). "Among several genetic abnormalities, both KRAS and ERBB2 amplification have been indicated as early events in adenocarcinoma development of Barrett's Esophagus." (PMID 22014070, 2011). "Progress in targeted therapy in esophageal adenocarcinoma has been slow primarily due to failure of conventional markers in other gastrointestinal adenocarcinoma (KRAS, EGFR, PTEN, PIK3CA, and c-MET) to identify patients with esophageal adenocarcinoma who would respond to a targeted therapy." (PMID 28404924, 2017).
mucinous adenoma (10 papers, 2013 to 2025). "Among the controls, two patients (6%), both with a mucinous cystadenoma, were found to have a KRAS variant in their surgical specimen." (PMID 36384753, 2022). "KRAS is mutated in 41–100% of appendiceal mucinous adenomas." (PMID 33712927, 2021).
Thrombocytopenia (10 papers, 2012 to 2025). A reduction in the number of circulating thrombocytes. "Here, we report our experience with a patient who suffered from recurrent fever, pallor, abdominal distention, leukocytosis, and thrombocytopenia with a silent past history and family history of somatic KRAS mutation." (PMID 33327329, 2020). "CES identified a somatic, pathogenic variant of KRAS (c.37G>T, p.Gly13Cys, variant allele frequency 19.6%) from a patient with unknown cause of anemia and thrombocytopenia (Incidental case 1), which made the genetic diagnosis of RAS-associated lymphoproliferative disorder." (PMID 37325673, 2023). "The patient who died had multiple high-risk features (severe thrombocytopenia and elevated fetal hemoglobin) and acquired additional somatic mutations that included JAK3, TERT, KRAS, and CBL, and eventual transformation to AML." (PMID 39123476, 2024). "In the cBioPortal cohort the proportion of patients with thrombocytopenia < 100 G/L was higher in patients with a KRAS mutation as compared to patients without a mutation." (PMID 40694264, 2025). "In this report, we describe a non-malignant somatic variant in KRAS with prominent clinical features of massive splenomegaly, thrombocytopenia and lymphopenia." (PMID 33472608, 2021). "However, the proportion of patients with thrombocytopenia was higher in KRAS-mutated patients in the BIOPORTAL cohort but not in the ABCMML cohort." (PMID 40694264, 2025).
adenosquamous carcinoma (9 papers, 2011 to 2024). A carcinoma composed of malignant glandular cells and malignant squamous cells. "Among the 312 NSCLC patients, the KRAS mutation rate was 5.77% (18/312), which included 16 adenocarcinomas and two adenosquamous carcinomas." (PMID 23951022, 2013). "Somatic mutations in KRAS were identified in 3 (6.3%) of 48 cervical adeno/adenosquamous cell carcinomas." (PMID 21730982, 2011). "Somatic mutations in either KRAS or BRAF were identified in 4 (8.3%) of 48 adeno/adenosquamous cell carcinomas." (PMID 21730982, 2011). "Controversies exist regarding the presence of KRAS mutations in LSCC; some data suggest that KRAS mutations may be misclassified as LUAD or adenosquamous carcinoma." (PMID 39544292, 2024). "Lenkiewicz’s study of adenosquamous carcinoma of the pancreas suggested that mutations in the KRAS gene provide a therapeutic target for adenosquamous carcinoma, which may provide new directions for the treatment of colorectal adenosquamous carcinoma." (PMID 38229035, 2024). "Here we present syngeneic graft models of aggressive, metastasis-prone histopathology-specific NSCLC tumor types driven by KRAS mutation and loss of LKB1 (KL): adenosquamous carcinoma (ASC) and adenocarcinoma (AC)." (PMID 36355420, 2022). "The frequencies of KRAS and BRAF mutations were very low in both squamous and adeno/adenosquamous cell carcinomas." (PMID 21730982, 2011).
Alzheimer disease (9 papers, 2017 to 2026). A progressive, neurodegenerative disease characterized by loss of function and death of nerve cells in several areas of the brain leading to loss of cognitive function such as memory and language. "Signaling by ERBB2 and KRAS play important roles in the development and progression of Alzheimer’s Disease." (PMID 36227739, 2022).
ampullary cancer (9 papers, 2012 to 2023). "The most notable mutation is an activating KRAS (Kirsten rat sarcoma viral oncogene homolog) mutation at codon 12 (G12V), which is one of the most commonly reported mutations in ampullary carcinomas." (PMID 22762308, 2012). "KRAS mutation is seen in up to 17% of bile duct cancers and up to 52% of ampullary cancers." (PMID 25890023, 2015). "Interestingly, three of the four ampullary cancers harboured dual HER2 mutations based on central sequencing, one of which also had an activating KRAS co-mutation." (PMID 36746967, 2023). "Two other studies have demonstrated KRAS mutations to be associated with poor prognosis in ampullary cancer;13,14 however, none of these considered tumor morphology." (PMID 32914025, 2019).
bile duct cancer (9 papers, 2014 to 2025). "In a previous study, we attempted to predict a primary site based on histopathology, IHC examinations, KRAS mutation, elevation of tumor markers (CA19-9 and CEA), and metastatic site distribution to distinguish gastric, pancreatic, and bile duct cancer profiles." (PMID 36899286, 2023). "KRAS is a crucial member of the RAS gene family, and somatic KRAS mutations are found in about 30% of human cancers, especially in lung, pancreatic, colorectal, and bile duct cancers." (PMID 36686734, 2022).
ductal carcinoma (9 papers, 2012 to 2024). "Mutations in KRAS are common in human ductal carcinoma and confer failure of sunitinib treatment in transgenic mouse models and possibly explain decreased response in some people to sunitinib." (PMID 34380474, 2021). "For example, mutations in the KRAS gene occur often in ductal carcinoma." (PMID 39576832, 2024).
intraepithelial neoplasia (9 papers, 2012 to 2025). A precancerous neoplastic process that affects the squamous, glandular, or transitional cell epithelium without evidence of invasion. "For instance in some lesions with high grade intraepithelial neoplasia and KRAS mutation that displayed high c-MYC and SIRT1 expression, no nuclear beta-catenin was detected, whereas other lesions with equally high c-MYC and SIRT1 levels were positive for nuclear beta-catenin (data not shown)." (PMID 23045412, 2012). "The current study showed that KRAS expression was significantly higher in OSCC compared to oral leukoplakia with epithelial dysplasia." (PMID 36532636, 2022). "KRAS mutations lead to constitutive activation of the RAS protein, resulting in activation of the RAF/MEK/ERK pathway or PI3K/PDK1/AKT/mTOR pathway and, ultimately, the development of intraepithelial neoplasia." (PMID 39941707, 2025). "Interestingly, in wild type BRAF and KRAS lesions with high grade intraepithelial neoplasia, moderate to strong c-MYC expression correlated with nuclear beta-catenin localization." (PMID 23045412, 2012). "Constitutively activated KRAS subsequently upregulates the endogenous expression of the upstream protein epidermal growth factor receptor (EGFR) and induces its hyperactivation, and increased RAS levels and EGFR activity induce robust increases MEK/ERK activity, leading to intraepithelial neoplasia." (PMID 33008426, 2020). "Taken together, sessile serrated lesions with and without intraepithelial neoplasia were more often located in the right colon (72% right sided versus 26% left sided) and frequently showed BRAF mutations (72% BRAF mutation versus 6 % KRAS mutation)." (PMID 23045412, 2012).
Lewis lung carcinoma (9 papers, 2018 to 2025). "Altogether, our data shows that treatment with a tumour-specific KRAS inhibitor can dramatically remodel the TME in favour of antitumour immune response, even in an immune cold tumour model such as the 3LL Lewis lung carcinoma." (PMID 34625563, 2021).
lung adenoma (9 papers, 2009 to 2022). A benign, well circumscribed epithelial neoplasm that arises from the bronchus or the lung parenchyma. "Systemic delivery of LNA-anti-miR-21 combined with only two doses of cisplatin over 7 weeks in these mice completely abolished the onset of lung adenomas and hyperplasia, denoting that miR-21 plays a major role in KRAS-mediated lung tumorigenesis." (PMID 29440633, 2018). "We finally sought to verify whether our findings could also be recapitulated in two different mouse models of human NSCLC, namely the model of urethane-induced pulmonary adenoma and of mutant KRAS-induced pulmonary adenocarcinoma." (PMID 26147201, 2015).
lung tumors (9 papers, 2005 to 2021). "It is tempting to hypothesize that LOH of FLCN, concomitant with oncogenic mutations in EGFR or KRAS, might allow low-grade lung neoplasms to progress to invasive adenocarcinomas." (PMID 26974543, 2016).
myeloid leukemia (9 papers, 2015 to 2025). A clonal proliferation of myeloid cells and their precursors in the bone marrow, peripheral blood, and spleen. "We propose that it is important to investigate these mechanisms in other cancer entities where KRAS is less frequently mutated, such as myeloid leukaemia." (PMID 33116132, 2020). "Surprisingly, a very recent study demonstrated that USP22 deficiency leads to myeloid leukemia upon oncogenic KRAS activation through a PU.1 dependent mechanism." (PMID 31842906, 2019). "Using genetic mouse models as well as patient samples, we observed that the NLRP3 inflammasome had a key role in the development of several features of KRAS-mutant myeloid leukaemia including cytopenia, splenomegaly and myeloproliferation." (PMID 33116132, 2020). "In agreement with our observations in mice, patient-derived myeloid leukemia cells exhibit KRAS/RAC1/ROS/NLRP3/IL-1β axis activity." (PMID 32246016, 2020).
oral cancer (9 papers, 1991 to 2024). "Along with our findings, KRAS has also been found to be associated with cell invasion, tumorigenesis, and lymph node metastasis in oral cancer." (PMID 37461111, 2023). "Das and colleagues reported that the frequency of mutation in the KRAS gene of oral cancer including tongue cancer was 33%." (PMID 31338331, 2019). "Although the cross-talk between IL-1RA and KRAS in oral cancer remains unclear, the underlying mechanism deserves further exploration." (PMID 37461111, 2023). "Although KRAS gene mutations are infrequent in OSCC, several studies have shown that miRNA binding site polymorphisms in KRAS were associated with reduced survival time in oral cancer." (PMID 36532636, 2022). "In the oral cancer cells (HSC4, OSC19) that were used in this study, high expression of EGFR was confirmed, but no mutations of BRAF, HRAS, KRAS, and NRAS were observed." (PMID 32878053, 2020).
thyroid (9 papers, 2012 to 2025). "The objective of the study was to determine if the analysis of mutations (BRAF, NRAS, KRAS and HRAS) using readily available molecular techniques can help better classify indeterminate thyroid nodules." (PMID 26621130, 2015). "The role of RAS oncogenes (KRAS, NRAS, and HRAS) in thyroid tumorigenesis has been well established." (PMID 39941320, 2025). "Regarding the selected genes in other CNA/UPD areas, the AKT3/PIK3CA pathway, the KRAS/RAP1B/RAP1GAP/BRAF pathway, and the VEGFC pathway have been known to participate in thyroid carcinogenesis/cancer progression." (PMID 22558328, 2012).
carcinosarcoma (8 papers, 2013 to 2025). A malignant tumor composed of a mixture of carcinomatous and sarcomatous elements. "Of note, the only case with BRCA mutation with a non-HRD dominant signature was a carcinosarcoma with KRAS amplification and a RAS-MAPK dominant signature." (PMID 35965534, 2022).
colorectal polyps (8 papers, 2006 to 2022). "The prevalence of KRAS mutations is discrete, ranging from 15% to 75% in colorectal polyps in previous studies." (PMID 35402217, 2022). "In our series of colorectal polyps, we found that mutations in KRAS, PIK3CA or BRAF are mutually exclusive and occur in the majority of these pre-malignant colorectal lesions." (PMID 18782444, 2008). "In our series of colorectal polyps we found the majority (71%) harbour mutations in KRAS (35.3%), PIK3CA (5.9%) or BRAF (29.4%) genes." (PMID 18782444, 2008). "The KRAS gene mutation frequency in colorectal polyps increases in proportion to their size." (PMID 16404419, 2006). "The population-based mutation rates of KRAS and BRAF genes in colorectal polyps within this Chinese patient population were 21.8% and 12.1% respectively." (PMID 26910894, 2016). "We aimed at determine the frequency of KRAS, BRAF and PIK3CA mutations in the process of colorectal tumourigenesis using a series of colorectal polyps and carcinomas." (PMID 18782444, 2008). "It was reported that APC and KRAS mutations in colorectal polyps were more frequent among smokers compared to non-smokers." (PMID 29258461, 2017). "Mutations in KRAS, PIK3CA or BRAF occur in 12 (70.6%) of the 17 colorectal polyps." (PMID 18782444, 2008). "The frequency of KRAS mutations found in the MSI and MSS CRC was not statistical different from the frequency found in colorectal polyps (P = 0.2014 and P = 0.7497, respectively)." (PMID 18782444, 2008).
gastrointestinal stromal tumor (8 papers, 2014 to 2023). "About 10–15% of adult, and most pediatric, gastrointestinal stromal tumors (GIST) lack mutations in KIT, PDGFRA, SDHx, or RAS pathway components (KRAS, BRAF, NF1)." (PMID 27974047, 2016). "Gastrointestinal stromal tumors with a KRAS mutation do not respond to imatinib treatment." (PMID 36900287, 2023).
kidney cancer (8 papers, 2012 to 2025). Primary or metastatic malignant neoplasm involving the kidney. "Interestingly, as of March 21, 2021 there were only 46 publications containing the key words of “KRAS” or “K-RAS”, either in title or in abstract among the > 42,000 publications with renal/kidney cancer-related key words in the title." (PMID 34384473, 2021). "Interestingly, while KRAS in RCC is understudied to date, AKT is a much more popular study area (18 publications with KRAS or K-ras in Title versus 168 publications with AKT in Title from over 42,000 kidney cancer publications as of March 21, 2021)." (PMID 34384473, 2021).
papilloma (8 papers, 2011 to 2022). A benign epithelial neoplasm that projects above the surrounding epithelial surface and consists of villous or arborescent outgrowths of fibrovascular stroma. "Indeed, in transgenic mice harboring the mutated KRAS in the K15+ follicular stem cells, IL27 promoted faster visible papilloma incidence and induced higher ETAR expression in the CD11b-positve cells in the pre-malignant skin." (PMID 27738312, 2016).
small bowel cancer (8 papers, 2009 to 2024). "However, in this study, although the KRAS mutation rate in small bowel cancer reached 41.8%, there was no G12C mutation detected, which was different from the G12C mutation rate of 3.1% in previous study." (PMID 35359599, 2022). "Given the limited role of anti-EGFR therapies in KRAS wild-type small bowel cancers or for right-sided colon cancers, anti-EGFR therapies for KRAS wild-type ampullary adenocarcinomas are not recommended." (PMID 38136318, 2023).